PURA (purine rich element binding protein A)
Diseases named in the same sentence as PURA in open-access papers (continued):
Sharing a sentence is not in itself a finding about the gene and the disease.
tumor (13 papers, 2014 to 2025). "Other studies have stated that the aromatic amino acid (aroA) and purine (purA) pathways of Salmonella enterica are also of relevance in the bacterium’s establishment within the tumor, since mutations in these metabolic pathways lead to a decrease in bacteria in the tumor tissue." (PMID 36077761, 2022). "PURα is associated with many types of neoplasias and brain development." (PMID 24819879, 2014). "For ESCC, G699-0288 inhibits the interaction between MEST and PURα, exhibiting a strong anti-tumor effect in the PDX model with low toxicity." (PMID 39844051, 2025). "Although DNA/RNA binding proteins are hardly targeted, novel strategies have been applied to identify compounds targeting PURα and have demonstrated promising anti-tumor efficacy in the preclinical study." (PMID 39844051, 2025). "The same group further revealed that the expression level of cytoplasmic PURα in ESCC tumor tissues was significantly higher than in adjacent epithelia." (PMID 39000020, 2024). "Studies have found that overexpression of PURA inhibits proliferation and anchorage-independent colony formation of Ras-transformed NIH3T3 Fibroblast cells, suggesting PURA acts as a potential tumor suppressor gene." (PMID 38062391, 2023). "The expression level of cytoplasmic PURα in ESCC tumor tissues was significantly higher than that in adjacent epithelia and correlated with a worse patient survival rate by immunohistochemistry." (PMID 35945453, 2022). "Recent elucidation of the abnormal expression of PURα in ESCC helps to provide a basic-research support for the tumor progression." (PMID 33142842, 2020). "The findings implied that 20(S)-protopanaxadiol might be a promising PURα agonist and the potential anti-tumor function of 20(S)-protopanaxadiol was supposed to be evaluated on cancers where PURα was discovered as a tumor suppressor in preclinical studies." (PMID 39844051, 2025). "The oncogenic or tumor-suppressive functions of PURα are realized via regulating RNA/protein interaction, mRNA translation, formation of stress granules (SGs), and transcriptional regulation of several oncogenes and tumor suppressors." (PMID 39844051, 2025). "PURα strongly influences the development and progression of disease by regulating DNA replication, transcription and mRNA transport, but whether PURα participates in tumor progression by regulating mRNA-based processes remains unclear." (PMID 35945453, 2022). "Considering the negative regulation of PURα on the mRNA translation of IGFBP3 in the cytoplasm and the effect of IGFBP3 on tumor progression, we hypothesized that cytoplasmic PURα plays an oncogenic role by inhibiting the mRNA translation of IGFBP3 in ESCC." (PMID 35945453, 2022). "Mechanistically, AGPG physically activated E2F1 via interacting with PURα and blocking the binding of E2F1 to PURα, while AGPG inhibition significantly repressed tumor growth in the endocrine-resistant mouse model." (PMID 39119602, 2024). "Genes ASPH, HSPB1, SQSTM1, ANXA2, and GSN (Cluster A) and PURA and MX1 (Cluster B) were downregulated for both datasets in PCa tissue vs. normal gland or normal adjacent to tumor tissue." (PMID 32640729, 2020). "IHC staining showed that PURα protein levels were negative for most tumor samples of various subtypes." (PMID 39844051, 2025). "Based on the stimulatory effect of PURα on EMT and the important role played by PCK2 in tumor metabolism, PURα and PCK2 may represent new therapeutic targets for ESCC." (PMID 33142842, 2020). "However, the relationship and mechanism between PURα and tumor metabolism have not been elucidated, and research on the regulation of metabolic genes by PURα has not been reported." (PMID 33142842, 2020).
cancer (12 papers, 2013 to 2025). A tumor composed of atypical neoplastic, often pleomorphic cells that invade other tissues. "The mutation and aberrant expression of PURα contribute to cancer progression via multiple mechanisms including directly or indirectly regulating gene expression, initiating translation, and SGs formation, making it a promising therapeutic target for cancers." (PMID 39844051, 2025). "More importantly, unlike that in PURA-expressing cell lines, there was no change in the invasive and metastatic potential upon overexpression of MEST in PURA-deficient ESCC cells, and the promoting effects of MEST in cancer invasion and metastasis could be restored by re-overexpression of PURA." (PMID 37149929, 2023). "Studies have revealed aberrant expression of PURα in specific cancer types e.g., low PURα expression or gene deletion was observed in AML, Myeloid neoplasia (MN), hormone-refractory prostate cancer (HRPC), and BC, and high PURα expression was observed in ESCC." (PMID 39844051, 2025). "Several recent studies have uncovered novel molecular mechanisms of PURα in cancer cells which involved in cancer progression." (PMID 39844051, 2025). "For the past 5 years, studies emphasized several oncogenes as direct targets of PURα and have elucidated that the regulation is critical for cancer development." (PMID 39844051, 2025). "It has been observed in several cancer types about the dysregulation of PURA mRNA levels, is attributed to chromosome deletion in AML and MDS." (PMID 39844051, 2025). "Association with PURα strongly suppresses the ability of E2F1 to initiate the transcription of cell-cycle-related genes and affects the occurrence and development of cancer." (PMID 39844051, 2025). "As an RNA-binding protein, PURα also plays a crucial role in cancer progression by interacting with mRNA, mainly through influencing its translation." (PMID 39844051, 2025). "The present review summarizes the most recently discovered critical roles of PURα in various cancer types, providing an overview of the biomarker and therapeutic target potential of PURα for patients with cancer." (PMID 39844051, 2025). "In preclinical settings, knockdown or overexpression of PURα has shown a great impact on cancer cell proliferation, drug resistance, and metastasis." (PMID 39844051, 2025). "Via molecular docking, a compound (G699-0288) targeting the interaction between MEST and PURα has been identified, and G699-0288 inhibits cancer cell metastasis in vivo." (PMID 39844051, 2025). "Using human ESCC patients’ tissue, the expression of PURα positively correlated with lymph node metastasis and the American Joint Committee on Cancer stages." (PMID 39000020, 2024). "In HepG2 cells, miR-23a and miR-27a induced cell cycle progression by directly targeting PURA, implicating cancer cell proliferation by inhibiting cell cycle progression at G1-S or G2-M checkpoints, resulting in increased HCC cell growth." (PMID 39112518, 2024). "The role of PURA in cancer, in particular, in transcriptional regulation, is complex and context dependent; for example, PURA can function as a transcriptional activator for some genes, including TGFβ1,53 TNFα,54 and β2-integrin." (PMID 37149929, 2023). "Taken together, our results demonstrate that MEST regulates SRCIN1/RASAL1-ERK-snail signaling and cancer metastasis in a PURA-dependent manner." (PMID 37149929, 2023). "It has been commonly reported that PURα is involved in the progression of several cancers as a transcription factor." (PMID 35945453, 2022). "Purα is an important transcriptional activator, which means that Purα knockout has a considerable impact on many metabolic pathways involved in growth and development, such as pathways in cancer, PI3K-Akt signaling, and cytokine-cytokine receptor interaction." (PMID 34108502, 2021).
cancer (continued). "For let-7e-3p, cancer-associated genes such as MAPK1 and EZH2 were among the negatively correlated genes, and PURA, ERCC1 and MAPT were among the positively correlated ones." (PMID 24257477, 2013). "Therefore, IHC detection of PURα protein is a putative clinical method to predict hormone therapy resistance and cancer cell metastasis in certain cancer types." (PMID 39844051, 2025). "Therefore, dysregulation of DNA/RNA binding proteins such as purine-rich element binding protein alpha (PURα) disrupts signaling transduction and often leads to human diseases including cancer." (PMID 39844051, 2025). "The present review delivers a comprehensive summary of several facets of PURα, including its aberrant expression patterns in cancer, the regulations concerning its expression and activity, the core molecules responsible for the role of PURα in cancer cells, and the targeted approaches for PURα." (PMID 39844051, 2025). "Dysregulation of PURα has been observed in many cancer types, including PC, BC, and ESCC." (PMID 39844051, 2025). "Despite the well-known functions of PURα as a transcription co-factor and transcription factor, most recent studies also demonstrated the novel roles of PURα in the development of cancers, such as regulating translation initiation of mRNA and orchestrating stress granules." (PMID 39844051, 2025). "LncRNA PURA was an evolutionarily conserved cellular protein participating in processes of DNA replication, transcription, and RNA transport, which functioned in human cancer." (PMID 32802855, 2020). "Whether PURA gene deletion can be a biomarker for cancer needs further investigation." (PMID 39844051, 2025). "Considering to the multiple functions of PURα, including DNA transcription, duplication, and mRNA transport, the heterogenous functions among different types of cells might result in different effects of PURα on the progression of different cancers." (PMID 39000020, 2024). "The binding of MEST to PURα blocked the physical interaction between PURα and the promoters of SRCIN1 and RASAL1, leading to the activation of ERK signaling and cancer metastasis." (PMID 39844051, 2025). "Overall, these findings indicate that PURα promotes EMT and the transcriptional activation of the PCK2 gene in ESCC cells, while PCK2 can participate in the metabolic reprogramming of cancer cells." (PMID 33142842, 2020).
neurodevelopmental disorder (10 papers, 2021 to 2026). A behavioral and cognitive disorder with onset during the developmental period that involves impaired or aberrant development of intellectual, motor, or social functions. "PURA protein molecular variations have been linked to several neurodevelopmental disorders." (PMID 35884678, 2022). "Furthermore, this function fits very well with neurodegenerative and neurodevelopmental disorders described in association with the PURA protein." (PMID 33777106, 2021). "A recent article has identified high frequency of de novo mutations or variants (DNMs) in few genes which include PURA, SATB2, SCN1A, and TUBA1A and these are mostly found in cases of neurodevelopmental disorders (NDDs)." (PMID 39263390, 2024). "PURA syndrome which comprises PURA-related neurodevelopmental disorders (MIM600473), is caused by causative variants in the PURA gene; and 5q31.3 microdeletion syndrome, caused by 5q31.3 microdeletion which may encompass all, or part, of PURA." (PMID 40713824, 2025). "The role and localization of PURA in the synapses may influence not only the treatment of peripheral symptoms but may also be the key to treatment of cognitive aspects of PURA-related neurodevelopmental disorders." (PMID 36768582, 2023). "Although these neurodevelopmental disorders are not considered chromatinopathies, it is worthy of note that PURA and RECQL4 are transcriptional regulators, and helicases are considered a guardian of the genome, such that they are involved in proper chromatin maintenance." (PMID 33959609, 2021).
Neurological Diseases (3 papers, 2021 to 2025). "This rare neurological disease results from mutations in the PURA gene located on chromosome 5, leading to haploinsufficiency of the PUR-a protein." (PMID 39531550, 2024).
hematologic malignancies (1 paper, 2022). "PURA and PURB are nucleic acid-binding proteins that form nucleoprotein complexes associated with hematologic malignancies and hyperproliferation." (PMID 35831314, 2022).
movement disorder (1 paper, 2025). Neurological conditions resulting in abnormal voluntary or involuntary movement, which may impact the speed, fluency, quality and ease of movement. "Although the pathomechanism of seizure has been described in PURA(+/−) mice; hyperacusis and movement disorders remain unstudied in PURA-related research." (PMID 40713824, 2025).
PURA also shares sentences with these, for which no sentence is quoted: frontotemporal dementia (3 papers); Autosomal dominant mental retardation 31 (2); cutis laxa (2); fragile X-associated tremor/ataxia syndrome (2); Neurodevelopmental delay (2); allergic disease (1); Allergy (1); asthma (1); atopic dermatitis (1); COVID-19 (1); Dystonia (1); Epileptic spasm (1); esophageal cancer (1); genetic disease (1); Hypotonia (1); infantile spasms (1); learning disability (1); Macrocephaly (1); memory impairment (1); Menkes disease (1); microcephaly (1); neurodegenerative disease (1); progressive multifocal leukoencephalopathy (1); psoriasis (1); Respiratory insufficiency (1); speech disorder (1); syndromic epilepsy (1).